FMC1-LUC7L2 (FMC1-LUC7L2 readthrough)
Synonyms: C7orf55-LUC7L2
Gene: Protein-coding gene on chromosome 7 (139,341,360 to 139,422,599, forward strand). Ensembl gene ENSG00000269955.
Genetic constraint (gnomAD): Loss-of-function variants: 28 observed, 59.33 expected, observed/expected ratio (o/e) 0.47, 90% interval 0.35 to 0.65. The upper end of that interval is the gene's LOEUF score, 0.65, which puts it in group 2 of 6, group 1 being the genes least tolerant of losing a copy. Missense variants: 431 observed, 608.82 expected, observed/expected ratio (o/e) 0.71, 90% interval 0.65 to 0.77. Synonymous variants: 167 observed, 203.91 expected, observed/expected ratio (o/e) 0.82, 90% interval 0.72 to 0.93.